AKAP10 (A-kinase anchoring protein 10)
Description:
Differentially targeted protein that binds to type I and II regulatory subunits of protein kinase A and anchors them to the mitochondria or the plasma membrane. Although the physiological relevance between PKA and AKAPS with mitochondria is not fully understood, one idea is that BAD, a proapoptotic member, is phosphorylated and inactivated by mitochondria-anchored PKA. It cannot be excluded too that it may facilitate PKA as well as G protein signal transduction, by acting as an adapter for assembling multiprotein complexes. With its RGS domain, it could lead to the interaction to G-alpha proteins, providing a link between the signaling machinery and the downstream kinase (By similarity).
Synonyms: AKAP-10; D-AKAP-2; PRKA10; D-AKAP2; MGC9414
Tractability: Antibody: its Gene Ontology location is reachable by antibodies, with high confidence. PROTAC: ubiquitination databases record sites on it; its protein half-life has been measured.
Gene: Protein-coding gene on chromosome 17 (19,904,302 to 19,978,343, reverse strand). Ensembl gene ENSG00000108599.
Subcellular location: Mitochondrion; Membrane; Cytoplasm
Subcellular location (Human Protein Atlas): Cytosol; Plasma membrane
Pathways (Reactome):
Hemostasis: Factors involved in megakaryocyte development and platelet production
Gene Ontology:
Molecular function: protein binding; protein kinase A binding
Biological process: intracellular protein localization; signal transduction
Cellular component: cytosol; mitochondrion; protein-containing complex; cytoplasm; membrane
Genetic constraint (gnomAD): Loss-of-function variants: 17 observed, 66.89 expected, observed/expected ratio (o/e) 0.25, 90% interval 0.17 to 0.38. The upper end of that interval is the gene's LOEUF score, 0.38, which puts it in group 1 of 6, group 1 being the genes least tolerant of losing a copy. Missense variants: 608 observed, 745.34 expected, observed/expected ratio (o/e) 0.82, 90% interval 0.76 to 0.87. Synonymous variants: 264 observed, 258.17 expected, observed/expected ratio (o/e) 1.02, 90% interval 0.92 to 1.13.
Homologues: Orthologues: chimpanzee AKAP10 (99% identical), macaque AKAP10 (98% identical), dog AKAP10 (95% identical), rabbit AKAP10 (93% identical), guinea pig AKAP10 (92% identical), mouse Akap10 (90% identical), pig AKAP10 (89% identical), rat Akap10 (86% identical), tropical clawed frog akap10 (71% identical), zebrafish akap10 (64% identical), Drosophila melanogaster pkaap (24% identical), Caenorhabditis elegans rgs-5 (21% identical).
Diseases named in the same sentence as AKAP10 in open-access papers:
AKAP10 is named in the same sentence as 18 diseases in open-access papers, as found by Europe PMC text mining. Sharing a sentence is not in itself a finding about the gene and the disease. The quoted sentences say what the papers report.
breast carcinoma (5 papers, 2015 to 2024). "In recent decades, genetic variants of AKAP10 have been associated with cardiac arrhythmias, breast cancer, and preterm birth." (PMID 39259428, 2024). "For example, using gene editing techniques to correct mutations in the AKAP10 allele may decrease risk for breast cancer and colorectal cancer, but at the cost of increasing the risk of pre-term birth." (PMID 38952711, 2024). "Furthermore, the AKAP13 K526Q SNP, along with I646V in AKAP10, further augmented the risk for breast cancer." (PMID 29370121, 2018). "Additionally, the valine AKAP10 variant carriers were also found to have increased risk of developing familial breast cancer." (PMID 29370121, 2018). "Specific polymorphisms in AKAP10 and in particular in combination with a SNP in AKAP13 were shown to be associated with increased risk for familial breast cancer." (PMID 29433456, 2018). "A number of these AKAPs have been reported to correlate with the occurrence of different cancer subtypes, including AKAP3 (ovarian cancer), AKAP4 (multiple myeloma), AKAP9 (breast cancer), AKAP10 (breast cancer) and AKAP13 (colorectal cancer and breast cancer)." (PMID 26272591, 2015).
cardiac arrhythmia (4 papers, 2011 to 2024). Any disturbances of the normal rhythmic beating of the heart or MYOCARDIAL CONTRACTION. "Mice carrying the same allele show cardiac arrhythmias and die prematurely, which suggests that AKAP10 plays an essential role in the control of heart rhythm and which makes it an interesting medical target." (PMID 21423752, 2011). "As an example, we find a DNA-binding domain in the C-terminal part of the A-kinase anchor protein 10 (AKAP10), a PKA adaptor that has been implicated in cardiac arrhythmias and premature cardiac death, which upon stress likely translocates from mitochondria to the nucleus/nucleolus." (PMID 21423752, 2011).
colorectal cancer (4 papers, 2015 to 2024). A primary or metastatic malignant neoplasm that affects the colon or rectum. "The same polymorphism in AKAP10 (Ile646Val) was also found to be associated with colorectal cancer risk." (PMID 29433456, 2018). "AKAP10 was significantly increased in colorectal cancer patients and polymorphism (2073 A/G, I646V) was associated with colorectal cancer risk." (PMID 25900241, 2015). "Overexpression of PKA RIα and AKAP10 in several colorectal cancer cell lines is directly correlated to metastasis." (PMID 33292604, 2020). "The mRNA and protein levels of PKA RIα and AKAP10 are significantly increased in colorectal cancer tissues, correlating with invasion depth, differentiation degree and short survival." (PMID 33292604, 2020).
myocardial infarction (2 papers, 2012 to 2018). Gross necrosis of the myocardium, as a result of interruption of the blood supply to the area, as in coronary thrombosis. "In another study of a larger cohort of Japanese individuals, it was revealed that valine at 646 of AKAP10 was significantly associated with higher cases of myocardial infarction (MI) than in people with no history of hypercholesterolemia." (PMID 29370121, 2018).
artery disease (1 paper, 2021). "The variants c.1936A>G on AKAP10 and c.575A>G on PON1 are linked to defects in cardiac conduction and artery disease, respectively." (PMID 33466296, 2021).
prostate carcinoma (1 paper, 2020). A carcinoma that arises from epithelial cells of the prostate gland. "Results from TCGA samples indicated a significant correlation between XPC and AKAP10 in prostate cancer." (PMID 32488882, 2020). "There is a significant correlation between XPC and AKAP10 in prostate cancer." (PMID 32488882, 2020).
pulmonary stenosis (1 paper, 2018). "Another recent research report identified SNPs in AKAP10 in fetuses with ventricular septal defects and pulmonary stenosis, suggesting AKAP10 as a potential target for these cardiac conditions." (PMID 29370121, 2018).
cancer (1 paper, 2024). A tumor composed of atypical neoplastic, often pleomorphic cells that invade other tissues. "Recognizing this duality of effects may allow us to recommend treatment schedules such as one in which an AKAP10-focused genetic treatment to reduce cancer risk be delayed until after child-bearing years to avoid the increased risk of pre-term births." (PMID 38952711, 2024).
AKAP10 also shares sentences with these, for which no sentence is quoted: Arrhythmia (1 paper); Bradycardia (1); cardiovascular disease (1); coronary heart disease (1); heart disease (1); influenza (1); long QT syndrome (1); metastatic tumors (1); tumor (1); ventricular septal defect (1).